ZRSR2 (zinc finger CCCH-type, RNA binding motif and serine/arginine rich 2)
Description:
Pre-mRNA-binding protein required for splicing of both U2- and U12-type introns. Selectively interacts with the 3'-splice site of U2- and U12-type pre-mRNAs and promotes different steps in U2 and U12 intron splicing. Recruited to U12 pre-mRNAs in an ATP-dependent manner and is required for assembly of the pre-spliceosome, a precursor to other spliceosomal complexes. For U2-type introns, it is selectively and specifically required for the second step of splicing.
Synonyms: URP; U2AF1-RS2; U2AF1L2; U2AF1RS2; ZC3H22; OFD21
Tractability: PROTAC: UniProt records ubiquitination sites on it; ubiquitination databases record sites on it.
Gene: Protein-coding gene on chromosome X (15,790,106 to 15,830,694, forward strand). Ensembl gene ENSG00000169249.
Subcellular location: Nucleus
Pathways (Reactome):
Metabolism of RNA: mRNA Splicing - Minor Pathway
Gene Ontology:
Molecular function: identical protein binding; pre-mRNA 3'-splice site binding; protein binding; metal ion binding; nucleic acid binding; RNA binding
Biological process: mRNA splicing, via spliceosome; spliceosomal complex assembly; RNA splicing
Cellular component: U11/U12 snRNP; U12-type spliceosomal complex; nucleoplasm; spliceosomal complex; U2AF complex; nucleus
Homologues: Orthologues: chimpanzee ZRSR2 (99% identical), macaque ZRSR2 (99% identical), pig ZRSR2 (87% identical), rabbit ZRSR2 (87% identical), dog ZRSR2 (86% identical), guinea pig ZRSR2 (79% identical), mouse Gm73394 (67% identical), rat Zrsr2-ps1 (66% identical), tropical clawed frog zrsr2 (61% identical), zebrafish zrsr2 (55% identical), Drosophila melanogaster CG3294 (29% identical). Paralogues in human: U2AF1 (21% identical), U2AF1L4 (15% identical).